ARID1B (AT-rich interaction domain 1B)
Diseases named in the same sentence as ARID1B in open-access papers (continued):
Sharing a sentence is not in itself a finding about the gene and the disease.
cancer (continued). "Based on our patient cohort it seems unlikely that pathogenic germline variants in ARID1B confer an increased cancer risk, but longer follow-up of our patients is needed to make a definitive statement." (PMID 30349098, 2019). "ARID1A and ARID1B are typically co-expressed in cancer, but cancer driven by ARID1A mutation retains at least one functional ARID1B allele." (PMID 29890703, 2018). "Among the genes with the mutations identified, they include Cancer Gene Census genes and other cancer-associated genes with three of which carried multiple mutations (ARID1B, CSMD1 and ADAM17)." (PMID 30627328, 2018). "The authors also proved maintenance of ARID1B expression in tissues with ARID1B mutation, which is probably due to remaining wild-type allele, therefore, suggest a haploinsufficient role of ARID1B in cancer." (PMID 28521285, 2017). "Since SWI/SNF components are frequently mutated or deleted in cancer, we decided to confirm that Arid1b knockdown prevented senescence using two shRNAs targeting murine Arid1b." (PMID 27737960, 2016). "Exciting new evidence is emerging from the discovery that ARID1A-mutant cancer cells are highly vulnerable to loss of ARID1B expression, and similarly for BRG1/SMARCA4-mutated cancers to the loss of BRM/SMARCA2." (PMID 25927994, 2014). "While concurrent mutations in their encoding genes (ARID1A and ARID1B) may co‐occur in tumours, a synthetic lethal interaction between these paralogs has been identified, wherein ARID1B deficiency selectively eliminates ARID1A‐mutant cancer cells." (PMID 41578412, 2026). "The most common example of these interactions is provided by the combination of mutually exclusive gene paralogues, such as in cancers with ARID1A mutation that require ARID1B for survival or tumors with BRG1 deficiency, which are sensitive to SMARCA2 depletion." (PMID 41278204, 2025). "Mutations in ARID1A/ARID1B/ARID2 render cancers more prone to immune checkpoint blockade therapies." (PMID 41278204, 2025). "A previous study demonstrated that ARID1B exhibits specific vulnerability in human cancers with ARID1A mutations, and that ARID1A deficiency may make cancer cells more dependent on ARID1B." (PMID 38365747, 2024). "Somatic variants in ARID1B have been associated with several types of cancer." (PMID 39669611, 2024). "It is worth noting that the ARID1A-deficient cancers are susceptible to the perturbance of homolog ARID1B, indicating that synthetic lethality may be a possible therapeutic option in these specific tumors." (PMID 35303910, 2022). "The correlation analysis of immune cell infiltration and immune checkpoint gene expression showed that the infiltration rates of the main ICI subtypes, cancer-associated fibroblast, and myeloid cells were significantly enriched and correlated with ARID1B in COAD." (PMID 36313455, 2022). "Moreover, studies also suggest that ARID1B can be a particularly interesting target in ARID1A-mutated cancers." (PMID 36605718, 2022). "Indeed, ARID1A is the most commonly mutated SWI/SNF subunit in cancer, altering transcriptional regulation that cannot be covered by the ARID1B paralog." (PMID 34070411, 2021). "However, ARID1A or ARID1B mutations and the resultant functional deficiencies were tightly associated with the sensitive phenotype for cancer immunotherapy." (PMID 32791957, 2020). "Interestingly, high ARID1B expression is associated with poor outcomes in bladder urothelial carcinoma and it also predicts the benefits of adjuvant chemotherapy for this cancer." (PMID 32162380, 2020). "In addition, ARID1A and ARID1B alleles are frequently co-mutated in cancer, but ARID1A-deficient cancer retains at least one functional ARID1B allele." (PMID 29890703, 2018). "We also found a significant correlation between the loss of ARID1A immunoreactivity and reduced ARID1B levels, suggesting that ARID1B could be a target for anti-cancer therapy." (PMID 29890703, 2018).
cancer (continued). "Furthermore, ARID1B has emerged as tumor suppressor, for its frequent mutations have been recently identified across various cancers." (PMID 28415691, 2017). "TCGA data show that missense mutation is most frequent type of mutation in ARID1B in cancers." (PMID 28521285, 2017). "Overall, the identification of novel mechanisms by which ARID1B loss restricts senescence could reveal vulnerabilities (e.g., nucleotide metabolism) useful to target cancers bearing mutations in SWI/SNF genes." (PMID 27737960, 2016). "Thus, a recent study demonstrated a synthetic lethal relationship between inactivating mutations of the homologs ARID1A and ARID1B, both in primary and cancer cells." (PMID 24979463, 2014). "However, studies have also indicated that double deletion of ARID1A and ARID1B can trigger rapid carcinogenesis in the liver and skin of mice, suggesting caution should be exercised when employing homologous therapy for treating cancers with mutated ARID1." (PMID 39779467, 2025). "Moreover, we highlight the cGAS-STING signaling pathway as a potential mediator of the immune-activated tumor microenvironment in ARID1B-deficient cells, further enhancing our understanding of the complex interplay between genomic alterations and the immune system in cancer." (PMID 38577613, 2024). "Based on the research above, we reasonably deduced that ARID1A or ARID1B mutation serves as a novel biomarker for ICIs treatment and could have a connection with factors that are proven to be associated with sensitivity to cancer immunotherapy." (PMID 32791957, 2020). "Moreover, the correlation between the loss of ARID1A immunoreactivity and reduced ARID1B levels indicates that ARID1B could be an attractive target for anti-cancer therapy." (PMID 29890703, 2018). "AT-interacting domain-rich protein 1A (ARID1A) and ARID1B (ARID1A/B), a pivotal subunit, have significant relevance in cancer management because they are frequently mutated in a broad range of cancer types." (PMID 40087883, 2025). "Patients with high ARID1B expression exhibited significantly higher enrichment scores for both cell proliferation and cancer progenitor cell‐related pathways compared to those with low ARID1B expression." (PMID 40671262, 2025). "ARID1B exists in the SWI/SNF chromatin remodeling complex in an exclusive manner with ARID1A and has been identified as a major mutated gene in various cancers in recent years." (PMID 39932052, 2025). "For HPV-associated SNSCC with matched normal DNA the most frequently mutated COSMIC cancer driver genes included KMT2D (4/12 patients, 33%), FGFR3 and KMT2C (3/12 patients, 25%), GOLGA5, TET1, and ARID1B (2/12 patients, 16.7%)." (PMID 40500270, 2025). "To understand the role of ARID1B in cancer development, we initially examined the gene expression profiles of ARID1B in pan‐cancer patients and analyzed its differential expression across various cancers." (PMID 40671262, 2025). "In cancer, subunits of chromatin remodelers are frequently mutated–for instance, ARID1A, ARID1B, and PBRM1 (components of the SWI/SNF complex) are mutated in various cancers." (PMID 41234540, 2025). "ARID1B OE significantly increased the number of spheroids and elevated the portion of CD44+/CD24‐ and ALDH‐positive cancer stem cell populations, suggesting that ARID1B plays a critical role in promoting cell survival and the maintenance of cancer stem cells." (PMID 40671262, 2025). "Surveying 829 polyclonal gastric microbiopsies by targeted sequencing, we find somatic 'driver' mutations in a distinctive repertoire of known cancer genes, including ARID1A, ARID1B, ARID2, CTNNB1 and KDM6A." (PMID 40108450, 2025). "Deletions of ARID1A and ARID1B drive hyperproliferation and dedifferentiation in several human cancers." (PMID 40362680, 2025). "The interplay between ARID1A and ARID1B in cancer has been a subject of research interest, showing functional redundancy in some contexts." (PMID 40671262, 2025).
cancer (continued). "ARID1A and its paralog ARID1B occupy the same position within the BAF complex and can functionally compensate for each other, which makes ARID1B essential to cancer cells following ARID1A mutation." (PMID 41387924, 2025). "ARID1A and ARID1B are components of the SWI-SNF complex that are involved in chromatin remodeling and are implicated in several human cancers." (PMID 38232086, 2024). "ARID1A-deficient cancer cells are vulnerable to the loss of ARID1B, such that a concomitant loss of ARID1A and ARID1B disturbs enhancer dynamics at growth promoting loci." (PMID 38390898, 2024). "ARID1B is a SWI/SNF subunit frequently mutated in human Coffin–Siris syndrome (CSS) and it is necessary for proliferation of ARID1A mutant cancers." (PMID 38347147, 2024). "For example, BRG1-mutated cancer cells are dependent on the presence of BRM, whereas ARID1A-mutated cancer cells are vulnerable to the deletion of ARID1B." (PMID 38396925, 2024). "The binding of the macrolactam inhibitor, BD98, phenocopied some features of ARID1A/ARID1B loss and synergized with ATR inhibitors to kill a diverse array of cancer cells." (PMID 38390898, 2024). "ARID1A and ARID1B are frequently co-mutated in cancer, but ARID1A-deficient cancers retain at least one functional ARID1B allele." (PMID 36844227, 2023). "Several targeted agents have shown promise in the context of ARID1A‐deficient cancers, including inhibitors of YES1, cell cycle modulators and ARID1B." (PMID 38041544, 2023). "These included ARID1B, the paralog of which, ARID1A, is among one of the most frequently mutated genes in cancer, SMARCA4, and SMARCA2." (PMID 37500730, 2023). "While ARID1A mutations are well‐studied, the role of ARID1B in cancer and its potential as a therapeutic target in ARID1A‐deficient cancers are areas of ongoing research." (PMID 38041544, 2023). "ARID1B, as a component of a subset of cBAF complexes, is a homolog of ARID1A that promotes a compensatory pathway in the event of loss of ARID1A in some cancers." (PMID 36844227, 2023). "Generally, mutated ARID1A, ARID1B and ARID2 were all related to the good prognosis of ICI therapy based on the pan-cancer population." (PMID 35239432, 2022). "Although ARID1A has a mutually exclusive homolog ARID1B, and both ARID1A and ARID1B are often co-mutated in human cancers, the creation of specific inhibitors is challenging due to the 60% homology between ARID domains." (PMID 36430148, 2022). "GSEA revealed that ARID1B is involved in multiple cancer-related pathways, among others PI3K-AKT and mTOR pathways, suggesting that ARID1B regulates these pathways and functions as a tumour suppressor in COAD." (PMID 36313455, 2022). "ARID1B, a paralog of ARID1A, has been recently recognized as a putative lethal target for ARID1A-mutant cancers, as ARID1B depletion impairs growth and destabilizes the SWI/SNF complex, which subsequently increases cell radiosensitivity." (PMID 36249060, 2022). "Comparison of these findings with those of previous studies confirmed silenced expression of genes, especially ARID1B by aberrant methylation of DNA in cancer." (PMID 36313455, 2022). "Among the six SWI/SNF genes, ARID1A and SMARCB1 were, respectively, the most and least frequently mutated genes in the majority of the cancer types (ARID1A, 10.7%; SMARCA4, 6.0%; ARID1B, 4.7%; ARID2, 4.0%; PBRM1, 3.5%; SMARCB1, 1.3%)." (PMID 36371186, 2022). "ARID1B shares 60% sequence identity with ARID1A, also contains an ARID domain, and is also mutated (although at lower frequency) in a variety of cancers such as basal cell carcinoma, melanoma, and some gynecological cancers." (PMID 36605718, 2022). "A recent study shows that ARID1B is a specific vulnerability in ARID1A mutant cancers, further highlighting the potential of synthetic lethal strategies for ARID1A mutation in cancer." (PMID 34671561, 2021). "Nevertheless, due to functional redundancy at enhancers, ARID1B is remarkably essential in ARID1A-deleted cancers." (PMID 34070411, 2021).
cancer (continued). "Through systematic analyses of the datasets from the cBioPortal for Cancer Genomics, we found that both ARID1A and ARID1B mutations were associated with an improved outcome for ICIs treatment in advanced NSCLC patients." (PMID 32791957, 2020). "Further investigations into the role of ARID1B in cancer immunotherapy are needed, given the small sample size in this research." (PMID 32791957, 2020). "This indicates that the presence of ARID1B is necessary for stabilizing the SWI/SNF complex in ARID1A-mutant cancer cells." (PMID 32245111, 2020). "Mammalian SWI/SNF complexes are composed of 12–15 subunits, and mutations in subunit genes including ARID1A, SMARCA4, ARID1B, ARID2, and PBRM1 occur across a wide spectrum of human cancers." (PMID 33381446, 2020). "Loss of ARID1B in ARID1A-deficient backgrounds destabilizes SWI/SNF complexes and impairs cancer and primary cell proliferation." (PMID 33381446, 2020). "ARID1A and ARID1B are mutually exclusive, and few studies have been done to characterize the functional dependency between ARID1A and ARID1B in cancer." (PMID 31769422, 2019). "This suggests that the presence of ARID1B is essential for stabilizing the SWI/SNF complex in ARID1A-mutant cancer cells." (PMID 29890703, 2018). "ARID1A and ARID1B are the only known DNA-binding proteins in the SWI/SNF-A complex; inactivation of ARID1B in an ARID1A-deficient background can disrupt SWI/SNF complex activity, thereby contributing to the development and progression of human cancers." (PMID 29890703, 2018). "The recognition that ARID1B exhibits tumor suppressor property has motivated growing interest in the research area of cancer etiology." (PMID 28415691, 2017). "Knockdown of ARID1B led to a 70–80% reduction in ARID1B protein, which impaired cancer cell growth as previously reported." (PMID 28967863, 2017). "The tumor suppressor role of AT-rich interactive domain containing protein 1B (ARID1B) has drawn much attention in area of cancer etiology." (PMID 28415691, 2017). "The absence of SWI/SNF complexes dysregulates these processes, resulting in altered expression of key genes in cancer pathways, consistent with reduced cancer cell growth observed upon loss of ARID1A and ARID1B." (PMID 28967863, 2017). "The AT-rich interactive-containing domain (ARID) gene superfamily consists of seven members (ARID1–5), of which the following have now been implicated in cancer: ARID1A/BAF250a, ARID1B/250b, and ARID2/BAF200." (PMID 24622842, 2014). "Two important SWI/SNF complexes implicated in cancer are the BAF and PBAF complexes, which contain the mutually exclusive ARID1A or ARID1B subunits and PBRM1 or BRD7 subunits, respectively." (PMID 24622842, 2014). "Moreover, a cell migration assay demonstrated that upregulation of ARID1B significantly enhanced cancer cell migration, whereas ARID1B downregulation substantially reduced it." (PMID 40671262, 2025). "ARID1A is frequently mutated in various cancers; however, the functional relationship and synthetic lethality mechanism between ARID1A and its homologue ARID1B remain unclear." (PMID 39779467, 2025). "ARID1A and ARID1B mutations co-occur in patients from multiple cancer types and >30% of ARID1A-mutant cell lines harbor ARID1B-inactivating mutations; thus, even the combined loss of the paralogue pair is tolerated, and potentially beneficial to cancer cells." (PMID 40239999, 2025). "Notably, ARID1A has a mutually exclusive paralog subunit, ARID1B, which was identified as a major vulnerability in ARID1A-deficient cancer cell lines, suggesting that ARID1B is a therapeutic target in ARID1A-deficient cancers." (PMID 41017120, 2025). "The differential expression of ARID1B in pan‐cancer suggests that the role of ARID1B in cancer might be tissue‐specific." (PMID 40671262, 2025).
cancer (continued). "For example, the manipulation of the Armadillo repeats (ARM) domain of the ARID1B subunit may disrupt ARID1B interaction with other subunits in the SWI/SNF complex and induce synthetic lethality in ARID1A-deficient cancers." (PMID 41278204, 2025). "Studies using comprehensive analysis of cancer genome sequencing have identified loss-of-function mutations in either ARID1A and/or ARID1B in various cells, suggesting that they may encode products related to tumor development." (PMID 38365747, 2024). "In the literature only occasional cases of ARID1B patients with cancer are reported." (PMID 39669611, 2024). "Based on our cohort and literature, there is no indication that germline variants in ARID1B give an increased cancer risk at pediatric age." (PMID 39669611, 2024). "When grouping cancer genes into canonical cancer pathways, mutations in the SWI–SNF complex (for example, SMARCA4, ARID1B and SMARCB1) and certain members of the NOTCH signalling pathway (for example, EP300 and NCOR1) were under significant subclonal, but not truncal, selection in LUAD." (PMID 37046096, 2023). "Similar to the scenario of cell-type dependence on ARID1A, cancers displaying the highest ARID1B dependency score (lower than −0.5 or so) tend to have ARID1A mutations, further validating the close functional interaction between these two core subunits of the SWI/SNF complex." (PMID 36980292, 2023). "The SWI/SNF genes, ARID1A, ARID1B, ARID2, SMARCA4, SMARCB1, and PBRM1 were mutated in up to 21.8% of all the cancers, and SWI/SNF mutation carriers had significantly higher TMB values as well as higher TMB-H and MSI-H proportions than their SWI/SNF-non-mutant counterparts in several malignancies." (PMID 36371186, 2022). "Cancer patients harboring mutated ARID1A, ARID1B or ARID2 benefit more from cancer immunotherapy." (PMID 35239432, 2022). "Downregulation of ARID1A and ARID1B, the variant subunits of the BRG1/BRM-associated factor complex from the SWI/SNF chromatin remodelling family, in various cancer cells might lead to deficiency in DNA repair." (PMID 35127746, 2021). "Our results indicated that ARID1A and ARID1B could alter the biological behaviour of CHOL cells through epigenetic regulation of cancer stemness." (PMID 35127746, 2021). "Given the results reported in this research, we proposed that ARID1A and ARID1B might be equally important in cancer immunotherapy and the prognosis of NSCLC." (PMID 32791957, 2020). "Whether this correlation can be verified in NSCLC and the potential role of ARID1B in cancer immunotherapy remain to be further studied." (PMID 32791957, 2020). "On the other hand, Helming and colleagues found a synthetic lethal relationship of ARID1A and ARID1B in a subgroup but not in all of the analyzed ARID1A mutated cancer cell lines, describing ARID1B as a specific vulnerability in ARID1A-mutant cancers." (PMID 31796878, 2019). "Loss of ARID1B in an ARID1A-deficient background eliminates the intact SWI/SNF complex, indicating that ARID1B is essential for the formation or stabilization of an intact SWI/SNF complex and, thus, the survival of ARID1A-mutant cancer cell lines." (PMID 29890703, 2018). "It has been stated previously that ARID1B may be a potential therapeutic target for ARID1A mutant cancers." (PMID 29760405, 2018). "In addition to ADAM17, mutations of ARID1B and CSMD1 were identified in the SS samples isolated from 3 out of 8 cancer patients in this study." (PMID 30627328, 2018). "Interestingly, compared to ARID1A, mutations in ARID1B and ARID2 are rare in cancer, apart from in neuroblastoma and hepatocellular carcinoma." (PMID 28967863, 2017). "Silencing ARID1B impaired cellular proliferation in cancer cells with ARID1A mutations, but not in cells with wild-type ARID1A, suggesting that ARID1B is a potential therapeutic target for cancers with ARID1A mutation." (PMID 26384299, 2015).